RNASE13 (ribonuclease A family member 13 (inactive))
Description:
Does not exhibit any ribonuclease activity.
Synonyms: RAL1; HEL-S-86p
Tractability: Antibody: UniProt places it where antibodies can reach, with high confidence; UniProt predicts a signal peptide or a membrane-spanning region; its Gene Ontology location is reachable by antibodies, with medium confidence.
Gene: Protein-coding gene on chromosome 14 (21,032,818 to 21,034,807, reverse strand). Ensembl gene ENSG00000206150.
Subcellular location: Secreted
Gene Ontology:
Molecular function: RNA nuclease activity; nucleic acid binding
Biological process: defense response to Gram-positive bacterium
Cellular component: extracellular region
Genetic constraint (gnomAD): Missense variants: 183 observed, 196.2 expected, observed/expected ratio (o/e) 0.93, 90% interval 0.83 to 1.05. Synonymous variants: 64 observed, 71.74 expected, observed/expected ratio (o/e) 0.89, 90% interval 0.73 to 1.1.
Homologues: Orthologues: mouse Rnase13 (70% identical), rat Rnase13 (69% identical), dog RNASE13 (67% identical), guinea pig RNASE13 (60% identical). Paralogues in human: RNASE4 (22% identical), RNASE7 (22% identical), RNASE1 (21% identical), ANG (20% identical), RNASE8 (20% identical), RNASE9 (19% identical), RNASE2 (19% identical), RNASE6 (19% identical), RNASE12 (18% identical), RNASE10 (17% identical), RNASE3 (17% identical), RNASE11 (15% identical).
Diseases named in the same sentence as RNASE13 in open-access papers:
RNASE13 is named in the same sentence as 1 disease in open-access papers, as found by Europe PMC text mining. Sharing a sentence is not in itself a finding about the gene and the disease.
RNASE13 shares sentences with these, for which no sentence is quoted: inherited diseases (1 paper).